CD59 (CD59 molecule (CD59 blood group))
Diseases named in the same sentence as CD59 in open-access papers (continued):
Sharing a sentence is not in itself a finding about the gene and the disease.
bladder cancer (3 papers, 2010 to 2023). "CD59 was downregulated in the sEV fractions of bladder cancer patients in this biomarker discovery study." (PMID 37371512, 2023).
bone metastasis (3 papers, 2019 to 2023). Transfer of a neoplasm from its primary site to bones. "Of these, CD59, haptoglobin, and tetranectin showed a significantly large fold change in patients with bone metastasis, which we further verified through immunohistochemistry and ELISA." (PMID 31413735, 2019).
chronic inflammatory demyelinating polyradiculoneuropathy (3 papers, 2019 to 2025). A rare neurological disorder in which there is inflammation of nerve roots and peripheral nerves and destruction of the fatty protective covering (myelin sheath) over the nerves. "Conversely, neurological manifestations of CD59 deficiency may cause recurrent hypotonia due to demyelination, initially presenting as acute inflammatory demyelinating polyradiculoneuropathy (AIDP) and potentially progressing to chronic inflammatory demyelinating polyneuropathy (CIDP)." (PMID 40519381, 2025).
endothelial dysfunction (3 papers, 2021 to 2024). In vascular diseases, endothelial dysfunction is a systemic pathological state of the endothelium (the inner lining of blood vessels) and can be broadly defined as an imbalance between vasodilating and vasoconstricting substances produced by (or acting on) the endothelium. "Hypertensive diseases cause microvascular injury and endothelial dysfunction through glycosylation of the other molecules of C5b-9 (CD59)." (PMID 39200810, 2024). "For instance, the measurement of soluble CD59 in the serum of experimental animals would be beneficial for confirming the role of this protein in endothelial dysfunction and for further analysis of its diagnostic value in this regard." (PMID 39518935, 2024). "The combination of serum proteomic profiling via LC-MS and dot blotting microarrays may verify the diagnostic and prognostic value of soluble CD59 and discover other sensitive and specific biomarkers of endothelial dysfunction." (PMID 39518935, 2024). "The potential value of soluble CD59 as an endothelial dysfunction marker requires further verification in various experimental settings and EC types." (PMID 39518935, 2024). "We consider it important to highlight soluble CD59 as a promising biomarker of endothelial dysfunction, in particular under calcium stress." (PMID 39518935, 2024). "Taken together, these findings advance our knowledge of endothelial dysfunction triggered by calcium stress and suggest increased release of soluble CD59 and impaired export of BM components as putative features of dysfunctional endothelium." (PMID 39518935, 2024). "Further studies might investigate whether the other triggers of endothelial dysfunction also promote the detachment of CD59 and/or suppress ECM production by various EC types." (PMID 39518935, 2024). "Since CD59 is highly expressed on vascular endothelial cells, we propose that hemodynamic stress may lead to endothelial dysfunction and subsequent sCD59 release." (PMID 33306183, 2021). "Hence, shedding and/or glycation of CD59 from endothelial cells might represent a pathological event indicative of endothelial dysfunction and vulnerability to its triggers, such as calcium stress, uremia, or elevated amounts of pro-inflammatory cytokines in the milieu." (PMID 39518935, 2024).
head and neck squamous cell carcinoma (3 papers, 2021 to 2025). A squamous cell carcinoma that arises from any of the following anatomic sites: lip and oral cavity, nasal cavity, paranasal sinuses, pharynx, larynx, and salivary glands. "For example, head and neck squamous cell carcinoma (HNSCC) cells express significantly elevated levels of CD46, CD55 and CD59, when compared to benign keratinocyte cells." (PMID 33802004, 2021).
influenza infection (3 papers, 2007 to 2017). "Mice that are genetically deficient in CD59 show increased lung immunopathology following influenza infection." (PMID 22984588, 2012). "Influenza infection of Balb/c.Cd59a–/– mice replicated the previous findings with B6.Cd59a–/– mice in that the degree of cellular infiltration was enhanced in mice deficient for CD59 compared to their WT counterpart (data not shown)." (PMID 17429844, 2007).
ischemia (3 papers, 2010 to 2023). A hypoperfusion of the BLOOD through an organ or tissue caused by a PATHOLOGIC CONSTRICTION or obstruction of its BLOOD VESSELS, or an absence of BLOOD CIRCULATION. "It was recently shown that ischemia leads to a rapid loss of membranous CD59 protein in the ischemic core region." (PMID 20202211, 2010).
leukemia (3 papers, 2017 to 2019). A malignant (clonal) hematologic disorder, involving hematopoietic stem cells and characterized by the presence of primitive or atypical myeloid or lymphoid cells in the bone marrow and the blood. "In one patient, the CD59-deficient cell clone disappeared 3 years earlier, and for the other one in the same year leukemia was diagnosed." (PMID 30116241, 2018). "The same can be said for the blockade of CD59 with neutralizing mAb and neuroblastoma, leukemia, breast, ovarian, and renal cancers." (PMID 31164885, 2019).
neuropathy (3 papers, 2021 to 2025). A disorder affecting the nervous system that manifests with pain, tingling, numbness, and/or muscle weakness. "CD59 deficiency is a rare autosomal recessive disorder causing complement-mediated hemolysis, strokes, and neuropathy." (PMID 40519381, 2025). "A complete absence of complement‐regulatory CD59 causes recurrent ischemic strokes, neuropathy, and chronic hemolysis." (PMID 40739794, 2025). "Lack of a functional CD59 protein causes recurrent ischemic strokes, neuropathy, and chronic hemolysis." (PMID 40739794, 2025). "Specific monoclonal antibodies detected glycated CD59 colocalising with MAC in kidneys and nerves from diabetic but not non-diabetic subjects, implicating glycation-mediated CD59 inactivation in complement-mediated diabetes-related nephropathy and neuropathy." (PMID 34159399, 2021).
neutropenia (3 papers, 2012 to 2016). A decrease in the number of neutrophils found in the blood. "Our patient had neutropenia with a normal lymphocyte count and did not seem to have PNH as she had no discrete PNH clone, despite diminished expression of CD59 on erythrocytes and CD55-CD59 expression on neutrophils." (PMID 25330534, 2014).
type 2 diabetes (3 papers, 2009 to 2025). "Indeed, the expression of complement receptor 3 on monocytes from non-insulin-dependent diabetes patients was strongly decreased and the CD55 and CD59 complement regulatory protein-positive monocytes were lower in type 2 diabetic patients." (PMID 20877467, 2010).
acute pneumonia (2 papers, 2021 to 2024). "The expression levels of CD28, CD59, LAG3, TCRab and TIGIT were higher, while CD45, CD45RO, RORγ, OX40 and Tbet lower in cluster 16 in acute pneumonia, stable pneumonia, acute asthma and stable asthma." (PMID 34841705, 2021). "The expression levels of CD27, CD28, CD59, OX40, CD40L, CD270, PD‐1, Tim3, EOME, HLA‐DR, TCRab and TIGIT were higher, while CD45, CD45RO and Tbet were lower in cluster 18 of patients with acute pneumonia." (PMID 34841705, 2021). "The expression levels of CD59, CD28, CCR7, CD270, Tim3, Eomes, lymphocyte activation gene‐3 (LAG3), TCRab and TIGIT were higher, while that of OX40, CD45RO, PD‐L1 and CD25 lower in cluster 09 in patients with acute pneumonia." (PMID 34841705, 2021).
adenocarcinomas of the prostate (2 papers, 2010 to 2021). "Increased cytoplasmic expression of CD59 is associated with reduced survival in colorectal cancer patients and with decreased overall survival in patients with adenocarcinomas of the prostate." (PMID 34572075, 2021). "They concluded that: “CD59 protein is strongly expressed in 36% of adenocarcinomas of the prostate and and is associated with disease progression and adverse patient prognosis”." (PMID 20805891, 2010). "Interestingly, CD59 was strongly expressed in 36% of adenocarcinomas of the prostate and associated with disease progression and adverse patient prognosis." (PMID 34572075, 2021). "CD59 tumor overexpression is correlated with decreased overall survival in patients with adenocarcinomas of the prostate." (PMID 34572075, 2021).
aneurysm (2 papers, 2009 to 2016). Bulging or ballooning in an area of an artery secondary to arterial wall weakening. "Since vascular smooth muscle apoptosis and inflammation have been demonstrated to be important mechanisms in human AAA, upregulation of Dapk1 and Cd59 may be relevant to the predilection of the suprarenal aorta to aneurysm formation in ApoE-/- mice." (PMID 19580648, 2009).
Arthritis (2 papers, 2006 to 2018). Inflammation of a joint. "Moreover, injection into the rat knee joint of an anti-rat CD59 mAb induces a spontaneous complement-dependent arthritis, and CD59-deficient mice are prone to enhanced antigen-induced arthritis." (PMID 16859540, 2006). "Injection of anti-rat CD59 induced spontaneous complement-dependent arthritis and mice lacking CD59 are susceptible to antigen-induced arthritis." (PMID 29892280, 2018).
autoimmune myasthenia gravis (2 papers, 2016 to 2023). "In the actively immunized experimental autoimmune myasthenia gravis mice deficient in either CD55 or CD59, a significant increase in complement deposition at the end-plates was observed and worsened disease outcome associated with increased levels of serum cytokines was observed." (PMID 27056040, 2016).
diabetic retinopathy (2 papers, 2013 to 2019). "Recent studies have described elevated levels of membrane attack complex (MAC) and reduced levels of membrane associated complement regulators including CD55 and CD59 in the retina of diabetic retinopathy patients as well as in animal models of this disease." (PMID 24167638, 2013).
esophageal squamous cell carcinoma (2 papers, 2018 to 2024). Esophageal squamous cell carcinoma (ESCC) is a type of esophageal carcinoma (EC) that can affect any part of the esophagus, but is usually located in the upper or middle third. "High CD59 expression indicated poor overall survival (OS) and disease-free survival (DFS) in esophageal squamous cell carcinoma (ESCC) patients who received radiotherapy." (PMID 30166523, 2018).
experimental autoimmune encephalomyelitis (2 papers, 2019 to 2021). An autoimmune demyelinating disease of the central nervous system that is produced experimentally in animals by the injection of homogenized brain or spinal cord in Freund's adjuvant. "Also, CD59-deficient mice show MAC deposits in the perivascular tissue in the areas of demyelination, and are more susceptible to experimental autoimmune encephalomyelitis, inflammation and axonal loss than wild type mice." (PMID 30794663, 2019).
gastric adenocarcinoma (2 papers, 2020 to 2024). "Additionally, Notch1 had a positive correlation with CD4, GATA3 and STAT5B and a negative correlation with CD59 in gastric adenocarcinoma." (PMID 32028262, 2020).
HCMV infection (2 papers, 2017 to 2018). "Expression of TRE17, a ubiquitin-specific protease known for regulating both ARF6 and CIE cargo trafficking to the PM, rescued CD147 and, to a lesser extent, CD59 trafficking from SEs in the context of HCMV infection." (PMID 30042195, 2018). "HCMV infection increased the frequency of coincidence of CD59 with TF546 to ~20% and 25% at 35 and 60 min postinternalization, respectively." (PMID 30042195, 2018). "However, during HCMV infection, CD59 accumulated in the SE as indicated by the increased association with EEA1 over time postuptake." (PMID 30042195, 2018).
head and neck cancer (2 papers, 2023 to 2025). A primary or metastatic malignant neoplasm affecting the head and neck. "Only CALML5 showed significant prognostic value, while the prognostic value of CD59 and LIMA1 could not be validated in this cohort, emphasizing the necessity to assess the head and neck cancer specificity by subgroup analysis." (PMID 37274282, 2023).
HIV-1 infection (2 papers, 2010 to 2024). The type species of lentivirus and the etiologic agent of acquired immunodeficiency syndrome (AIDS). "Indeed, upon HIV-1 infection of this cell line, we observed the downregulation of miRNA-26a expression (~2-fold less, p = 0.0286) and the concomitant upregulation of CD59 mRNA (3.5-fold, p = 0.0079) and surface protein levels." (PMID 39066239, 2024). "Given the critical inhibitory regulatory function of CD59 in CML and the fact that its expression is upregulated during HIV-1 infection of CD4+ T lymphocytes, we examined the impact of CD59 expression on the susceptibility of HIV-1-infected cells and released virions to ADCML." (PMID 39066239, 2024). "Taken together, these results indicate that HIV-1 infection of CD4+ T cells induces the upregulation of CD59 receptor at the mRNA and cell surface protein levels, and this condition appears to be linked to the downregulation of miRNAs, namely miRNAs-21, -26a and 29a, predicted to target CD59." (PMID 39066239, 2024).
Hypertension (2 papers, 2016 to 2024). The presence of chronic increased pressure in the systemic arterial system. "In agreement, a reduced expression of CD59 in endothelial cells from hypertensive patients has been described, suggesting a potential role in development of hypertension and increased CV risk." (PMID 26772976, 2016).
infarction (2 papers, 2020 to 2021). A localised pathological necrosis of tissue resulting from obstruction of the blood supply usually by a thrombus, an embolus, or vascular torsion. "Then, a marked tissue deposition of MAC associated with the progressive CD59 depletion was highlighted in infarction aged 20 h and more." (PMID 33147886, 2020).
injury (2 papers, 2009 to 2020). Damage inflicted on the body as the direct or indirect result of an external force, with or without disruption of structural continuity. "CR1 and CD59 were significantly reduced in the first week after acute brain injury." (PMID 33362763, 2020). "However, the biological significance of CD59 in protecting from complement-mediated neuropathology after traumatic brain injury is far from being fully understood." (PMID 19133139, 2009).
ischemic stroke (2 papers, 2019 to 2025). A stroke disorder caused by obstruction of blood flow to the brain, due to thrombotic (local blood clot formation) or embolic (due to a blood clot or other material traveling from another site) event. "Congenital CD59 deficiency is an extremely rare and recently described disease characterized by hemolysis, recurrent ischemic strokes and relapsing immune-mediated polyneuropathy." (PMID 30794663, 2019).
liver cancer (2 papers, 2016 to 2020). An epithelial or non-epithelial malignant neoplasm that arises from the liver. "The results indicated that FASN was closely associated with liver cancer migration and invasion, and interacted with FSCN1, SIPA1, SPTBN1 and CD59." (PMID 32699531, 2020). "Knockdown of FASN in liver cancer reduced the expression of FSCN1, SIPA1, SPTBN1 and CD59." (PMID 32699531, 2020).
macular degeneration (2 papers, 2017 to 2021). Loss of vision in the central portion of the retina (macula), secondary to retinal degeneration. "Taken together, these data suggest that the neurodegeneration that accompanies inherited GPI anchor deficiency and germline CD59 deficiency may be complement-mediated, and may lend insight into the mechanism of neurodegeneration in macular degeneration and other neurodegenerative diseases." (PMID 28441409, 2017). "We have reported that in models of macular degeneration, acetylated microtubules prevent recycling of the complement-regulatory protein CD59 to the plasma membrane and inhibit membrane repair by lysosome exocytosis." (PMID 33822768, 2021).
oral cancer (2 papers, 2022 to 2025). "CD59 is a serine protease and a complement restriction factor that can be used as a relevant early-stage biomarker for oral cancer diagnosis." (PMID 40096320, 2025). "Endothelin-1 represents a potential biomarker for the development of OSCC in patients with oral lichen planus and IL-8, IL-1β, glycoprotein M2BP (Mac-2 binding protein), CD59, myeloid protein 14 (MRP14) and catalase as salivary biomarkers of oral cancer." (PMID 36412636, 2022).
oral squamous cell carcinoma (2 papers, 2021 to 2022). "CD59 has been evaluated as a salivary biomarker for oral squamous cell carcinomas together with M2BP, S100A9/MRP14, and catalase, achieving diagnostic sensitivity of 90%, specificity of 83%, and AUROCC of 0.93 for OSCC detection." (PMID 34359613, 2021). "The treatment of oral squamous cell carcinoma (OSCC) remains a great clinical challenge, and the malignant proliferation of OSCC cells can lead to the overexpression of CD59." (PMID 35387305, 2022).
ovarian tumors (2 papers, 2019 to 2025). "Indeed, CD59 immunoreactivity is detected in up to 50% of ovarian tumors and at the border areas between normal and malignant tissue." (PMID 40370471, 2025). "Complement‐mediated cell killing of breast, lung and ovarian tumour cells by combined trastuzumab and pertuzumab was previously shown to be efficient only when all three CD46, CD55 and CD59 mCRPs were suppressed using the siRNA gene silencing technology." (PMID 31365168, 2019).
Parkinson’s (2 papers, 2020 to 2024). "CD4+ genes inversely associated with the PRS for Parkinson’s included DOCK8 and CD59." (PMID 38590520, 2024).
peritonitis (2 papers, 2017 to 2023). Inflammation of the peritoneum (tissue that lines the abdominal wall and covers most of the organs in the abdomen). "Peritoneal biopsies were additionally evaluated for CD46, CD55, and CD59 expression depending on their history of PD-associated peritonitis." (PMID 28542228, 2017). "In peritoneal biopsy tissues obtained at PD catheter removal, we investigated the severity of peritonitis-associated peritoneal injuries and the expression of CRegs, CD46, CD55, and CD59 against peritoneal tissues without any episode of peritonitis." (PMID 37298097, 2023).
renal carcinoma (2 papers, 2020 to 2022). A carcinoma arising from the epithelium of the renal parenchyma or the renal pelvis. "Remarkably, the expression of CD59, C3aR and C5aR co-localized with PTX3 expression within the renal cancer tissue samples (respectively)." (PMID 32345771, 2020).
tuberculosis (2 papers, 2023). A chronic, recurrent infection caused by the bacterium Mycobacterium tuberculosis. "This first study on CD59 genetic SNPs and tuberculosis susceptibility found that the TT and CT genotypes containing the ancestral allele at rs10768024 loci had a significant risk of TB susceptibility." (PMID 37050931, 2023). "In clinical practice, we also pay attention to the elevated level of CD59 in tuberculosis patients, which is expressed not only in monocyte–macrophages but also in T cells." (PMID 37050931, 2023). "However, little is known about the value of complement regulatory protein (CD46, CD55, and CD59) in the differential diagnosis of tuberculosis." (PMID 36820087, 2023). "A case–control study was conducted to investigate the SNPs at CD59 rs1047581, rs7046, rs2231460, rs184251026, rs41275164, rs831633, rs704700, rs41275166, and rs10768024 by sequence-specific primer-polymerase chain reaction (SSP-PCR) in 900 tuberculosis patients and 1,534 controls." (PMID 37050931, 2023).
uterine serous carcinoma (2 papers, 2015 to 2024). "The study found that uterine serous carcinoma is characterized by high levels of mCRPs CD46, CD55, and CD59." (PMID 39337406, 2024). "Consistent with this view, recent data from our group in uterine serous carcinomas, a subset of biologically aggressive tumors histologically similar to CS, demonstrate overexpression of mCRPs CD46, CD55 and CD59 in the majority of the tumors." (PMID 26474755, 2015).